ABI1 (abl interactor 1)
Diseases named in the same sentence as ABI1 in open-access papers (continued):
Sharing a sentence is not in itself a finding about the gene and the disease.
cancer (continued). "Here, we discovered that Abi1 plays a positive role in regulating human smooth muscle cell migration, which is supported by previous studies on cancer cell migration." (PMID 32606387, 2020). "Studies in other cancer cells involving the role of Abi1 in cancer development in vitro and in vivo are also contradictory." (PMID 32276588, 2020). "Intra- and inter-core heterogeneity (i.e. mosaic pattern) were defined when cancer cells with decreased or retained ABI1 protein were observed within the same (intra) or different (inter) TMA cores and it was assessed manually." (PMID 31530281, 2019). "For example, ABI1 and TRIM33 were both known cancer genes and were included in the CGC list, but their mutation patterns in UCEC have been rarely reported, even in the most recent comprehensive studies." (PMID 25348067, 2014). "ABI-1 is located at 10p11.2 in humans and is a homolog to the mouse Abelson interactor 1 gene (Abi-1) It is one of the major regulators of actin cytoskeleton reorganization but its role in cancer progression and metastasis remains ill-defined." (PMID 23759955, 2013). "Furthermore, ABI1-mediated developmental processes are also dysregulated in cancer, suggesting developmental origins of systemic programs activated in malignancy." (PMID 39354505, 2024). "Also included is a brief note on alternatively spliced forms of ABI1 observed in cancer and their contributions to tumor suppression." (PMID 39354505, 2024). "The role ABI1 plays in regulating cell adhesion through BCR-ABL1 interaction may contribute to malignant behavior of cancer cells, including propensity to metastasize and resist treatment." (PMID 39354505, 2024). "Consistent with this, low ABI1 expression in some types of cancer is associated with negative patient outcomes." (PMID 39354505, 2024). "ABI1 overexpression is linked to negative cancer patient outcomes, including poorer prognosis and higher frequency of relapse." (PMID 39354505, 2024). "Together, this highlights cross-regulation of inflammatory signaling pathways in cancer that might uphold therapeutic resistance, and how adaptor proteins such as ABI1 interlink these processes." (PMID 39354505, 2024). "ABI1 is a key molecule that coordinates actin cytoskeleton reorganization and growth signaling, which explain the simultaneous dysregulation of PI-3 kinase and actin cytoskeleton in cancer." (PMID 33281863, 2020). "The ABI1 gene has been listed as one of the top splice-isoform dysregulated genes in human cancer." (PMID 31530281, 2019). "In particular, we predict isoform switches that affect the encoded protein for the cancer drivers CCND3, MYH11, MITF, RALGD5, ABI1, PRDM1 and PPARG, which may have implications for targeted therapy development." (PMID 25578962, 2015). "The difference in Abi1 expression between KRAS-muteted carcinoma and KRAS-mutated HPP, on the other hand, was not significant (p>0.1)." (PMID 22808230, 2012). "Interestingly, our panel included genes already described to be cancer predisposition genes (FAS, ITK, KIF1B, PGR and MET) or previously reported as playing important roles in cancer (ABI1, ARID5B, DNMT3A, HEY1, KDM5C, NCOA1, NUP98, and SLC34A2), or in DNA repair process (FANCF)." (PMID 30925779, 2019). "Interaction between ABI1 and ABL1 also affects centrosome organization during mitosis, a commonly dysregulated process in cancer." (PMID 39354505, 2024). "Considering these findings, we used proximity‐dependent labeling (PDL) to detail mechanistic links between ABI1 and SFKs, STAT3, and NF‐κB and uncovered fundamental insight into the role of this adapter protein in cancer." (PMID 36635880, 2023). "Upregulated ABI1 is observed in several different cancers, correlating with negative patient outcomes." (PMID 39354505, 2024).
cancer (continued). "ABI1 can regulate actin aggregation and cytoskeleton reconstruction by forming complexes with WAVE2, PI3K, EPS8, and/or N-WASP17,20,23,24, and thus play an important role in the metastasis of various malignant tumors including CRC8–12,27,29,37." (PMID 34031495, 2021). "Our results point rather toward a cytoplasmic upregulation of Abi1 during colorectal tumorigenesis but interestingly, overexpression in KRAS-mutated carcinoma and metastasis was not significant compared to KRAS-mutated precursor lesions." (PMID 22808230, 2012). "ABI1 plays a multi-regulatory role in this context, enabling signaling crosstalk to affect processes including phosphoinositide 3-kinase (PI3K), EGFR, WRC-mediated cytoskeletal remodeling, and protein kinase B (AKT)-mediated cell survival and proliferation pathways dysregulated in cancer." (PMID 39354505, 2024). "Abi1 expression in carcinoma was independent of microsatellite stability of the tumor." (PMID 22808230, 2012).
tumor (23 papers, 2012 to 2025). "Overexpression of ABI1-212 results in increased cell adhesion, migration, and lung metastasis linked to altered actin dynamics through EPS8 interaction, consistent with loss of ABI1 tumor suppression capabilities." (PMID 39354505, 2024). "While reported as a tumor suppressor in the previous section, increased ABI1 expression is also associated with tumor metastasis, consistent with its role in regulating actin cytoskeleton organization." (PMID 39354505, 2024). "Previous research has found that loss of ABI1 contributes to tumor progression through regulation of the EMT-WNT pathway." (PMID 37158593, 2023). "The loss of ABI1 promoted an aggressive development in tumor cells, leading to shorter survival in GBM." (PMID 36233273, 2022). "Gain- and loss-of-function analysis revealed that downregulation of Abi1 contributes to the tumor suppressor effect of PTEN on the EMT and CSCs." (PMID 32728066, 2020). "Staining of a test tumor tissue microarray (32 cases) with ABI1 antibody demonstrated a remarkable loss of ABI1 expression in tumors with high Gleason grade." (PMID 31530281, 2019). "To investigate the molecular mechanism by which loss of ABI1 contributes to tumor progression, we disrupted the ABI1 gene in the benign prostate epithelial RWPE-1 cell line and determined its phenotype." (PMID 31530281, 2019). "Lymphatic and blood vessel invasion, representing significant prognostic variables in CRC, were independently associated with strong expression of Abi1 at the invasive margin of the tumours." (PMID 24913355, 2014). "ABI1 expression is associated with shorter survival time and higher frequency of tumor recurrence." (PMID 39354505, 2024). "Additionally, ABI1 knockdown in MDA-MB-231 cells is associated with slower murine tumor xenograft growth." (PMID 39354505, 2024). "In invasive CRC, we could show that expression and Y435 phosphorylation of Abi1 are associated with an aggressive tumor phenotype and promote tumor cell adhesion, extracellular matrix degradation, and invasion by CRC cells." (PMID 26345720, 2015). "Our analysis shows that Abi1 knockout (KO) mice, both with homozygous and heterozygous deletion had more diverse tumor growth kinetics compared to the controls." (PMID 34967509, 2022). "Most Abi1 KO PyMT mice demonstrated pulmonary metastasis within 6 months of the primary tumor detection." (PMID 34967509, 2022). "In this study, we set out to investigate the roles of ABI1-TSVs in regulating tumor metastasis and progression." (PMID 34031495, 2021). "ABI1 regulates tumor cell proliferation by binding to c-Abl14, v-Abl15, EPS816 and the p85 subunits of PI3K17." (PMID 34031495, 2021). "On the right an image demonstrating intra-core tumor heterogeneity of ABI1 expression with Benign, and Gleason 4 and 5 patterns; Benign, represents normal prostate tissue (VPC cohort)." (PMID 31530281, 2019). "To understand the mechanism by which ABI1 removal results in gain of an invasive phenotype in RWPE-1 cells, we investigated changes in RNA levels of known tumor-associated pathway genes." (PMID 31530281, 2019). "Levels of ABI1 expression in prostate organoid tumor cell lines was evaluated by Western blotting and RNA sequencing." (PMID 31530281, 2019). "We have previously shown that application of STI571/Glivec effectively inhibits CRC tumor cell invasion through the inhibition of Abi1 phosphorylation." (PMID 26345720, 2015). "Accordingly, we demonstrated that application of STI571/Glivec inhibited Abi1 tyrosine phosphorylation, extracellular matrix degradation, and tumor cell invasion in that study." (PMID 26345720, 2015). "Among the genes significantly co-activated in G3 basal-like tumor samples, we identified 3 reproducible and concordantly up-regulated SAGPs (ABI1/PDSS1, DIS3/BORA and WDR77/ATP5F1)." (PMID 26517092, 2015).
tumor (continued). "Together, these data are consistent with a potential tumor suppressor role for Abi1 in GBM, and raise a paradigm by which the non-canonical Crk pY251 pathway becomes functionally operational in tumor cells that down-regulate Abi1." (PMID 26473374, 2015). "In tumor tissue and cell lines, it has been shown that Abi1 contributes to leukemogenic potential in leukemic cells expressing oncogenic Bcr/Abl and v-Abl." (PMID 22808230, 2012). "Abi1 was strongly and ubiquitously expressed in the cytoplasm of most examined tumor samples and metastases." (PMID 22808230, 2012). "As with Abl kinases themselves, Abl kinase substrates such as Crk and ABI1 may have context-dependent tumor promoting or tumor suppressor functions." (PMID 37746268, 2023). "To elucidate the role of Abi1 gene dosage effect in lung metastasis, we first analyzed the tumor kinetic rates of the primary tumor growth vs. the largest tumor metastatic foci at 6 months within the same mice in Abi1 KO homozygous and heterozygous tumor groups." (PMID 34967509, 2022). "ABI1 acts as tumor suppressor in several other tissues such as prostate." (PMID 34967509, 2022). "ABI1 regulates tumor invasiveness through integrin signaling." (PMID 31530281, 2019). "Since none of members in SOS1/EPS8/ABI1 tri-complex is dispensable in the Rac activation, and ABI1 acts as a scaffold protein, we hypothesize that ABI1 may be an ideal target to design anti-tumor drugs." (PMID 31488087, 2019). "Additionally, multivariate testing ABA1 expression variation as a random function of CNA, ER status, and tumor subtypes showed that CNA in basal‐like tumor subtype samples provides a major explanatory contribution of ABI1 expression variation in our data (P < 1.00E‐6; two‐way ANOVA, Statistica 13)." (PMID 34967509, 2022). "Moreover, the apparent upregulation of ABI1 levels in the transition from benign to low grade tumors indicate a potential failsafe mechanism that initially prevents tumor progression, which when broken, leads to aggressive tumors with high metastatic potential." (PMID 31530281, 2019). "Interestingly, Abi1 can either positively or negatively contributes to tumor grade and progression depending on tumor types, but whether this reflects interaction with Abl or WAVE components is not defined." (PMID 26473374, 2015). "Together, these data suggest that Abi1 and Crk impart a reciprocal regulation on Abl kinase (Crk positively regulates while Abi1 negatively regulates), and that loss of the Abi1 gene in GBM functions in part by enhancing the Crk Tyr251 Abl axis to promote aggressive behavior in tumor cells." (PMID 26473374, 2015). "Quantitative Abi1 gene expression data for oesophageal (n = 13), gastric (n = 21), small intestinal (n = 6) and colorectal (n = 505) adenocarcinomas obtained from the GeneSapiens transcriptomics database showed comparable expression levels between tumour entities." (PMID 24913355, 2014). "Moreover, immunofluorescence microscopy revealed a strong staining signal for a phosphorylated isoform of Abi1 (Y435) at the leading edge of infiltrating tumours with high expression of Abi1, indicating a role for Abi1 tyrosine phosphorylation in CRC cell invasion." (PMID 24913355, 2014). "ABI1 is an essential part of the WAVE regulatory complex, a major promoter of actin filament nucleation is often exploited by invasive tumor cells." (PMID 34967509, 2022). "There are correlations of ABI1 expression with infiltration depth and degree of differentiation of CRC tumor, and CRC patients with high ABI1 expression have a lower 5-year survival rate and poorer prognosis." (PMID 34031495, 2021). "Most findings support a tumor-promoting function for Cortactin that might be linked to the essential role of the protein in invadopodia formation and maintenance, but the results for class I NPFs (N-WASP/WAVE), Abi1/2, and Cofilin are conflicting, especially in upper gastrointestinal tract tumors." (PMID 26345720, 2015).
tumor (continued). "Some of these switches occur in known tumor drivers, including PPARG, CCND3, RALGDS, MITF, PRDM1, ABI1 and MYH11, for which the switch implies a change in the protein product." (PMID 25578962, 2015). "Another possibility is that the complement of downstream Abl kinase substrates such as ABI1 and CRK may influence in which cell types Abl kinases may function as promoters versus suppressors of tumor progression." (PMID 37746268, 2023). "The staining of BRCA1, ABI1, and EIF3D was medium in tumor tissue but low in normal tissue." (PMID 36233273, 2022). "Based on our western blot findings, we next examined whether altered WAVE complex expression in the absence of ABI1 was recapitulated by immunohistochemical staining of tumor tissue." (PMID 34967509, 2022). "We also analyzed the reciprocal effects of Abi1 and Crk on Abl signaling in Abi1(−/−) MEFs reconstituted with Abi1 to rule out the possibility that other Abi1 isoforms may compensate for Abi1-Iso2 in the HS683 tumor cells." (PMID 26473374, 2015). "The presence or absence of the EPS8/SOS1/ABI1 complex acts as a molecular switch in PDAC cells to balance RAC1 and RhoA activation to promote tumor migration or TGFβ activation, respectively." (PMID 39354505, 2024).
infection (8 papers, 2015 to 2024). The state of being infected such as from the introduction of a foreign agent such as serum, vaccine, antigenic substance or organism. "The following subsections detail the major mechanisms by which ABI1 exploitation mediates infection." (PMID 39354505, 2024). "At 48 h post infection, there was a significant decrease in both ABI1 (p < 0.001) and ENAH (p < 0.01) expression." (PMID 37376546, 2023). "For analysed aba-insensitive mutants (abi1, abi2 and abi5), a reduction in the number of infection sites at 5 dpi, as well as the number of developed females and males, were observed." (PMID 37375924, 2023). "The decreased number of infection sites was found in abi1 (PP2C), abi2 (PP2C) and abi5 (transcription factor) signalling mutants, where an elevated expression of ABI2 and ABI5 genes was shown." (PMID 37375924, 2023). "For the abi1 mutant, the decrease of infection sites number to 58%, number of females to 63% and number of males to 57% were shown." (PMID 37375924, 2023). "For example, in the M1T3DS[T3DK] infection, the modulation of ABI1 and TBP ASE is respectively increased and decreased as compared to WT T3DS." (PMID 35489070, 2022). "Abi1 KD cells, c-Abl KD cells and cells expressing control shRNA were stable at least five passages after initial infection." (PMID 32606387, 2020). "Furthermore, Traes_3dl_8c6d663c5 (encoding a Protein Phosphatase 2C (PP2C), homolog to the A. thaliana ABI1), was repressed by infection in R tissues and less expressed in R infected spikelets compared to the S NIL." (PMID 29434615, 2018). "AnkA interacts with ABI1, and inhibition of ABL1 by siRNA knockdown or by imatinib impairs infection." (PMID 39354505, 2024). "To answer the question, we performed infection tests on wild type and ABA mutant roots and analysed the expression levels of selected ABA-related genes (ABI1, ABI2, ABI5, PYL5, PYL6, CYP707A1 and CYP707A4) at the early stage of root infection." (PMID 37375924, 2023). "In contrast, several ABA signaling mutants, such as abi1 and abi4, do not exhibit prominent phenotypes under the snc1-1 background or during pathogen infection." (PMID 26451844, 2015). "The time-course experiment revealed that upon adsorption and early during infection (4 h and 8 h), no significant modulation in the AS profiles of ABI1, CFLAR and IL34 could be detected." (PMID 35489070, 2022). "For example, upon infection with PcBMM, the expression of PAD3, PDF1-2 and PR1, but not CYP81F2, was enhanced in abi1/2 hab1 mkp1-1 in comparison to abi1/2 hab1, and the expression of PAD3 and CYP81F2 was higher in aba1-6 mkp1-1 than in aba1-6." (PMID 38576784, 2024).
adenocarcinoma (1 paper, 2014). A common cancer characterized by the presence of malignant glandular cells. "Taken together, these large-scale expression analyses confirm the strong expression of Abi1 that we previously reported for CRC among diverse adenocarcinomas of the gastrointestinal tract." (PMID 24913355, 2014).
ABI1 also shares sentences with these, for which no sentence is quoted: colorectal (2 papers); tubular adenoma (2); viral infection (2); anemia (1); brain disorder (1); colonic polyps (1); depression (1); Hodgkins lymphoma (1); intestinal cancer (1); liver cancer (1); melanoma (1); metastatic disease (1); prostatic intraepithelial neoplasia (1); psoriasis (1); sessile serrated polyp (1); stomach cancer (1).